VPS35 (VPS35 retromer complex component)
Diseases named in the same sentence as VPS35 in open-access papers (continued):
Sharing a sentence is not in itself a finding about the gene and the disease.
breast carcinoma (continued). "Dengjel and his colleagues used quantitative proteomics to identify Vps35/retromer as a stimulus-dependent interacting partner of autophagosomes in human breast cancer cells." (PMID 26658729, 2015). "We identified 6 autoantibodies that were present in mice prior to the development of mammary cancer: Pdhx, Otud6b, Stk39, Zpf238, Lgals8, and Vps35." (PMID 24886063, 2014). "This hypothesis aligns with studies showing that VPS35 promotes the proliferation of hepatocellular carcinoma, breast cancer and gastric cancer." (PMID 40484931, 2025). "Similarly, VPS35 promotes the progression of breast cancer and is essential for autophagy completion." (PMID 40484931, 2025). "Among them, VPS35 might exert as a significant oncogenic and prognostic factor for breast cancer and could be a promising autophagy-related therapeutic target in clinical practice." (PMID 34001111, 2021). "Further analyses were performed to clarify the biological function of VPS35 in breast cancer." (PMID 34001111, 2021). "VPS35 was upregulated in breast cancer cell lines compared with normal breast epithelia." (PMID 34001111, 2021). "Nonetheless, little is known about the association of VPS35 with cancer and there are no reports regarding the relationship between VPS35 and breast cancer up to now." (PMID 34001111, 2021). "We further confirmed the oncogenic role and function of VPS35 in breast cancer progression." (PMID 34001111, 2021). "And we speculated that VPS35 also might participate in regulating stemness properties of BCSCs through controlling autophagy process in breast cancer." (PMID 34001111, 2021). "To clarify whether VPS35 is a functional gene in breast cancer cells, we detected cancer cell proliferative abilities by CCK8 and colony formation assays, and cell migrative and invasive capacities by Transwell migration/invasion assays." (PMID 34001111, 2021). "Based on these, it let us select VPS35 as the target and we speculated that VPS35 may become a key oncogenic factor for the development and progression of breast cancer." (PMID 34001111, 2021). "To illustrate whether VPS35 acts as an oncogenic factor in breast cancer, we investigate the expression level of VPS35 in 52 pairs of breast cancer samples and the adjacent normal samples in the same patients by Western blot." (PMID 34001111, 2021). "VPS35 was overexpressed in breast cancer clinical samples compared with that in the normal tissues." (PMID 34001111, 2021). "However, little is known regarding the expression status, clinical and prognostic significance, and functional role of VPS35 in breast cancer and other cancers." (PMID 34001111, 2021). "Nevertheless, how VPS35 influencing the aggressiveness of breast cancer provokes our thought." (PMID 34001111, 2021). "In 2012, Dengjel used quantitative proteomics to identify VPS35 as a stimulus-dependent interacting partner of autophagosomes in human breast cancer cells, while a more recent study demonstrated that VPS35 directly interacts with and retrieves Atg8 in Magnaporthe oryzae." (PMID 26973516, 2016). "Hence, VPS35 may serve as a promising novel oncogenic factor, prognostic biomarker and therapeutic target for breast cancer." (PMID 34001111, 2021). "Therefore, we firstly investigated the role of VPS35 in breast cancer." (PMID 34001111, 2021). "Thus, VPS35 might increase the proliferative and invasive abilities of breast cancer cells mediating by autophagy regulation." (PMID 34001111, 2021). "Our findings illustrated that VPS35 promoted cell proliferative ability by clonal formation assay and VPS35 accelerated cell migration and invasion capacities by Transwell migration/invasion assays, suggesting that VPS35 is involved in the malignant process of breast cancer." (PMID 34001111, 2021). "Top-ranked Stem.Sig genes, such as EMC3, BECN1, VPS35, and PCBP2, showed improved immune response after knockout in melanoma, renal carcinoma, breast carcinoma, and colon adenocarcinoma from multiple CRISPR datasets." (PMID 35488273, 2022).
breast carcinoma (continued). "Five of these antigens (VPS35, ARPC2, SERBP1, KRT8, and PDIA6) were selected because they inhibited human breast cancer survival across two aggressive breast cancer subtype cell lines (HER2 positive and triple negative)." (PMID 33976232, 2021). "To further investigate the relationship between VPS35 and autophagy, we found that knockdown of VPS35 induced the transition of the LC3BI to LC3BII in breast cancer cells." (PMID 34001111, 2021). "We constructed VPS35 knockdown (shVPS35) breast cancer cell lines (MDA-MB-231 and SK-BR-3) by three virus-induced VPS35 shRNAs (shVPS35 1#; shVPS35 2#; shVPS35 3#) that target different regions of VPS35 mRNA." (PMID 34001111, 2021). "Four of the antigens (VPS35, SERBP1, KRT8, and PDIA6) decreased growth of the tumors in both mouse mammary tumor models." (PMID 33976232, 2021). "Consistent with the prediction results, VPS35 was positively correlated with lymph node metastasis and ER negative, indicating that VPS35 acts as an oncogenic factor in breast cancer development." (PMID 34001111, 2021). "There was a significant correlation of VPS35 expression with tumor size (p = 0.01), lymph node metastasis (p = 0.006), and ER negative (p = 0.043), indicating that VPS35 was involved in breast cancer development." (PMID 34001111, 2021). "Thus, we investigated whether VPS35 knockdown suppressed the migrative and invasive capacities of MDA-MB-231, which is a more aggressive breast cancer cell line, belonging to TNBC." (PMID 34001111, 2021).
hepatocellular carcinoma (7 papers, 2021 to 2026). A malignant tumor that arises from hepatocytes. "In line with this, another study demonstrated that the transcriptional activation of VPS35 by KLF7 propels hepatocellular carcinoma cells growth and metastasis by activating Ccdc85c-medicated β-catenin pathway." (PMID 40484931, 2025). "Specifically, VPS35 promotes the sorting and trafficking of transmembrane receptor, thereby augmenting the proliferation of hepatoma cell through the PI3K/AKT signaling pathway." (PMID 40484931, 2025). "In summary, KLF7/VPS35 axis contributes to hepatocellular carcinoma progression through CCDC85C-mediated β-catenin pathway." (PMID 33858520, 2021). "This invention provides an exosome with down-regulated VPS35 gene expression secreted by hepatocellular carcinoma cells, and mRNA molecule for the treatment of hepatocellular carcinoma." (PMID 34513718, 2021). "Only one study showed that VPS35 promoted the proliferation of hepatoma cells through the PI3K/AKT signaling pathway." (PMID 34001111, 2021). "Recently, it has been demonstrated that VPS35 participates in hepatocellular carcinoma tumor growth by activating PI3K/AKT signaling pathway." (PMID 33858520, 2021). "Moreover, VPS35 knockdown weakened SNX5-induced EGFR degradation in hepatocellular carcinoma (HCC)." (PMID 37950040, 2024).
neuroblastoma (7 papers, 2016 to 2023). Neuroblastoma (NB) is the most common solid, extracranial childhood tumor. "This motivated us to use CRISPR-Cas9–mediated genome editing to introduce the p.D620N variant in VPS35 into the human neuroblastoma SH-SY5Y cells widely used in PD research." (PMID 34127073, 2021). "Depletion of VPS35 in neuroblastoma cells also causes reduced basal Δψm and an increase in mitochondrial fission at steady state." (PMID 34127073, 2021). "Altered mitochondrial morphology and dynamics were detected in VPS35-deficient DA neurons, as well as VPS35-depleted neuroblastoma and fibroblast cell lines." (PMID 26973516, 2016). "We tested this assay on SH-SY5Y neuroblastoma cells, which allowed us to further test whether Parkin-dependent ubiquitination of VPS35 is conserved in human cells." (PMID 28399880, 2017). "Notably we identified VPS35 as an in vivo Parkin substrate, both in flies and in human neuroblastoma SH-SY5Y cells, reinforcing a connection between mitochondrial homeostasis and endo-lysosomal pathways in PD and AD." (PMID 28399880, 2017). "Consistent with the role of AIMP2 in mediating cell toxicity, we showed that coexpression of WT VPS35 but not mutant VPS35 prevented cell toxicity caused by elevated AIMP2 in SH-SY5Y neuroblastoma cell line." (PMID 28383562, 2017). "We previously reported that internalized DAT targets to retromer/Vps35+ endosomes and that intact retromer complex is required for DAT delivery to the plasma membrane in DAergic neuroblastoma cell lines." (PMID 36640864, 2023). "A similar degree of colocalisation was observed for PLD3–GFP and APP in neuroblastoma SH-SY5Y cells and PLD3–GFP was detected in endosomes positive for the retromer protein VPS35." (PMID 29368044, 2018).
tauopathies (7 papers, 2020 to 2025). "Another protein that was found associated with tau in all four major tauopathies is the core retromer complex protein VPS35." (PMID 40082954, 2025). "Probe-dependent proximity profiling of tau pathology found an association of vacuolar protein sorting-associated protein 35 (VPS35) with tau pathology across tauopathies." (PMID 40661559, 2025). "Among the phospho-tau associated proteins shared across tauopathies, we selected VPS35 and lysosome-associated membrane protein (LAMP2) for further studies." (PMID 40082954, 2025). "Similarly to LRRK2, VPS35 has been associated with tauopathies in in vivo and in vitro modelling." (PMID 34397087, 2021). "Our results reveal the association of retromer complex component vacuolar protein sorting-associated protein 35 (VPS35) and lysosome-associated membrane glycoprotein 2 (LAMP2) with specific types of phospho-tau lesions in tauopathies." (PMID 40082954, 2025). "Neuropathologic characterization of VPS35 and LAMP2 corroborates the mass spectrometry proteomics findings, confirming their association with AT8-positive aggregates in all four major tauopathies." (PMID 40082954, 2025). "We found an abnormal accumulation of VPS35 in several types of phospho-tau lesions in frontal cortices from all the studied tauopathies." (PMID 40082954, 2025). "A current report identified that VPS35 regulates tau phosphorylation and neuropathology in tauopathies, such as progressive supranuclear palsy (PSP) and Pick’s disease." (PMID 33032646, 2020). "Altogether, these data suggest that retromer complex disfunction is a characteristic feature of tauopathies, and VPS35 sequestration into phospho-tau pathological lesions may play an important role in pathogenesis of these disorders." (PMID 40082954, 2025). "Given these strong links to neurodegeneration, we decided to explore the association of VPS35 with phospho-tau lesions by co-immunostaining post-mortem frontal cortex sections across tauopathy cases with AT8 and VPS35 antibodies." (PMID 40082954, 2025).
dementia (5 papers, 2015 to 2025). Loss of intellectual abilities interfering with an individual's social and occupational functions. "An in-depth sequence analyses of all coding, noncoding, and exon–intron boundaries VPS35 genetic regions have been performed in a large well-characterized cohort of Lewy body disorders, including PD patients, PD with dementia, and dementia with Lewy bodies." (PMID 25980689, 2015).
amyotrophic lateral sclerosis (4 papers, 2016 to 2024). Amyotrophic lateral sclerosis (ALS) is a neurodegenerative disease characterized by progressive muscular paralysis reflecting degeneration of motor neurons in the primary motor cortex, corticospinal tracts, brainstem and spinal cord. "Following the identification of bis-1,3-phenyl guanylhydrazone 2a as an effective new compound for the treatment of amyotrophic lateral sclerosis, in this work we analyze the possible binding sites of this molecule to the VPS35/VPS29 dimer of the retromer complex." (PMID 38487369, 2024). "Our study reveals a critical yet unappreciated role for VPS35 function in the normal maintenance and survival of motor neurons during post-natal development that has important implications for neurodegenerative diseases, particularly amyotrophic lateral sclerosis." (PMID 34704029, 2021).
gastric cancer (4 papers, 2024 to 2026). A primary or metastatic malignant neoplasm involving the stomach. "Previous reports indicate that VPS35 contributes to gastric cancer and HCC progression 35,36." (PMID 40303303, 2025). "Furthermore, in gastric cancer cells, VPS35 expression is upregulated, and it positively regulates the proliferation and peritoneal metastasis of gastric cancer cells through integrin/FAK/SRC signalling-mediated IL-6/STAT3 pathway activation in a YAP-dependent manner." (PMID 40484931, 2025). "However, the function and molecular mechanism of VPS35 in gastric cancer (GC) remains largely unknown." (PMID 37950040, 2024). "We investigated the expression and prognosis in gastric cancer and adjacent normal tissues from Asian and non-Asian GC populations using GEO database and found VPS35 significant upregulation in GC." (PMID 37950040, 2024).
Hydrocephalus (4 papers, 2021 to 2023). Hydrocephalus is an active distension of the ventricular system of the brain resulting from inadequate passage of CSF from its point of production within the cerebral ventricles to its point of absorption into the systemic circulation. "Other studies reported that conditional knockout of Vps35 in ependymal cells activated microglia and caused hydrocephalus, while depletion of microglia rescued the pathology of hydrocephalus." (PMID 37008045, 2023). "Recently, it was reported that hydrocephalus caused by the loss of the ependymal Vps35 gene is reversible with PLX3397-mediated microglial ablation." (PMID 37296418, 2023). "Similarly, mice with a knock-out of vacuolar protein sorting-associated protein 35 (VPS35), a protein known to be critical for ependymal cell survival, developed enlarged lateral ventricles and microglial activation redolent of hydrocephalus." (PMID 34440681, 2021). "A very recent publication, that does not study AQP4, describes that young postnatal Vps35 conditional KO mice develop neonatal hydrocephalus, similar to that of Snx27−/− mice, with deficient ependymal cells differentiation and ciliogenesis." (PMID 34002021, 2021).
osteoporosis (4 papers, 2019 to 2025). A condition of reduced bone mass, with decreased cortical thickness and a decrease in the number and size of the trabeculae of cancellous bone (but normal chemical composition), resulting in increased fracture incidence. "Cuproptosis-related genes VPS35 impairs the availability and activity of WNT ligands, which might alter bone metabolism and contribute to osteoporosis." (PMID 40980812, 2025). "Additionally, the mRNA relative expression of CIR1, GPR27, and PDE8A were reduced in the osteoporosis group, while NIF3L1 and VPS35 were increased." (PMID 40980812, 2025).
depression (3 papers, 2020 to 2022). "Taken together, these results suggest that microglial VPS35 deficiency exacerbates cognitive disfunction (spatial learning and memory), but not anxiety- or depression-like behaviors, in VPS35CX3CR1:5xFAD mice." (PMID 35236374, 2022). "In addition, although there are several gene variants associated with the development of non-motor symptoms in PD patients (e.g., LRRK2, SNCA, Parkin, and VPS35), only a few studies have explored their effects on depression-like behavior in mice." (PMID 35645772, 2022). "To address the discrepancies in terms of results and methodologies in the VPS35 studies thus far, we first generated transgenic VPS35 D620N mice and then subjected them to a series of behavioral tests (focusing on levels of overall movement, motor coordination, anxiety, and depression)." (PMID 33261640, 2020).
viral infection (3 papers, 2021 to 2025). "The interaction between VPS35 and Ku in the cytoplasm may fine-tune Ku’s availability for nuclear DNA repair or play a role in immune surveillance, potentially modulating the cellular response to viral infections or mitochondrial DNA leakage." (PMID 40484931, 2025).
cognitive decline (2 papers, 2016 to 2022). "In summary, this study suggests that microglial VPS35 deficiency enhances Aβ pathology and accelerates cognitive decline in 5XFAD mice, an AD animal model, supporting the view for VPS35 deficiency as a risk factor for AD development." (PMID 35236374, 2022).
colon adenocarcinoma (2 papers, 2022 to 2026). "VPS35 was significantly highly expressed in 12 unpaired tumor tissues, including LIHC, colon adenocarcinoma (COAD), and stomach adenocarcinoma (STAD)." (PMID 41531939, 2026).
ischemic stroke (2 papers, 2019 to 2022). A stroke disorder caused by obstruction of blood flow to the brain, due to thrombotic (local blood clot formation) or embolic (due to a blood clot or other material traveling from another site) event. "We found that microglial VPS35 loss results in an increase of anti-inflammatory microglia in mouse cortex after ischemic stroke." (PMID 31771656, 2019). "Here, we report that microglial VPS35 loss regulates microglial polarization in the cortical brain after ischemic stroke." (PMID 31771656, 2019). "The ischemic stroke-induced brain injury phenotypes, including brain damage, neuronal death, and sensorimotor deficits, were all attenuated by microglial VPS35-deficiency." (PMID 31771656, 2019). "It is also noteworthy that not only Aβ induced DAM is impaired in microglial VPS35 KO 5XFAD mice, the ischemic stroke induced DAM was also diminished in microglial VPS35 KO cortex." (PMID 35236374, 2022). "We used mice with VPS35 cKO (conditional knockout) in microglial cells and examined and compared their responses to ischemic stroke with control mice." (PMID 31771656, 2019). "Further analysis of protein expression changes revealed a reduction in CX3CR1 (CX3C chemokine receptor 1) in microglial VPS35-deficient cortex after ischemic stroke, implicating CX3CR1 as a potential cargo of VPS35 in this event." (PMID 31771656, 2019). "In line with this view are our observations of decreased iNOS+ microglia and reduced expression of pro-inflammatory cytokines in VPS35 mutant brains after ischemic stroke." (PMID 31771656, 2019). "However, microglial VPS35’s role in the cortex in response to ischemic stroke remains largely unclear." (PMID 31771656, 2019). "In addition, ischemic stroke-induced increase of CX3CR1 receptor levels is abolished in microglial VPS35-deficient mice, implicating CX3CR1 as a potential cargo of VPS35." (PMID 31771656, 2019). "Ischemic stroke-induced injury is diminished in microglial VPS35 conditional knockout (cKO) mice." (PMID 31771656, 2019). "However, the function of microglial VPS35 in the cortex in response to ischemic stroke remains elusive." (PMID 31771656, 2019).
liver cancer (2 papers, 2024 to 2026). An epithelial or non-epithelial malignant neoplasm that arises from the liver. "Some articles suggest that inhibiting the function of the heat shock protein 90 (Hsp90) can promote the expression of VPS35 by upregulating Bclaf-1, thereby facilitating extracellular vesicle release in liver cancer cells." (PMID 38714741, 2024).
melanoma (2 papers, 2012 to 2022). A malignant, usually aggressive tumor composed of atypical, neoplastic melanocytes. "Transfecting A2058 cells with WNT3A leads to a 5.2-fold enhancement of BAR-luciferase, which was inhibited by siRNA-mediated knockdown of WLS and VPS35 suggesting that WLS-dependent WNT secretion regulates WNT/β-catenin signalling in melanoma." (PMID 23129487, 2012).
Onset (2 papers, 2012 to 2017). The age group in which disease manifestations appear. "Importantly, VPS35, which causes autosomal dominant, late-onset PD, is similarly involved in endosomal trafficking and has also recently been implicated in mitochondrial dynamics, including interactions with Parkin." (PMID 28137300, 2017). "Interestingly, mutations in VPS35, a component of the retromer complex, involved in retrograde transport, were recently reported as a cause of late-onset PD." (PMID 22457822, 2012).